ALB (albumin)
Diseases named in the same sentence as ALB in open-access papers (continued):
Sharing a sentence is not in itself a finding about the gene and the disease.
central obesity (35 papers, 2007 to 2026). "Although not statistically significant, we observed that the association between central obesity and albumin-creatinine ratio appeared slightly stronger among the Hindustani-Surinamese than among the other ethnic groups." (PMID 22564356, 2012). "Several potential pathophysiological pathways may support a causal link between abdominal obesity and increased urinary albumin excretion." (PMID 36034904, 2022). "Therefore, our findings of an association between WHtR or WC, as indices of central obesity, and the risk of microalbuminuria argue for an important role for visceral vs. peripheral fat in relation to albumin excretion." (PMID 23594567, 2013). "Interestingly, in obese subjects with the same percentage of total body fat, the risk of abnormal albumin excretion was 18 times higher in those with central obesity but only four times higher in subjects with peripheral obesity compared to controls." (PMID 23594567, 2013). "In the case of MUI, HbA1c mediated up to 6.34 and 6.08%, serum vitamin D mediated up to 8.33 and 7.61%, and serum albumin mediated up to 10.99 and 9.92%, under the general and central obesity definitions, respectively." (PMID 39469327, 2024). "The FPG, albumin, haemoglobin, BMI, WC and prevalence of abdominal obesity were significantly different between the two groups (P = 0.02, < 0.01, < 0.01, < 0.01, < 0.01 and < 0.01, respectively)." (PMID 35193560, 2022). "Regarding central obesity, a longitudinal study in China found that people with both central and peripheral obesity had higher risks of elevated urine albumin-creatinine ratio, even after adjusting for multiple factors (OR: 1.14, 95% CI: 1.07–1.21, p < 0.001)." (PMID 34869437, 2021). "Height, weight, WC, serum albumin, GNRI, and abdominal obesity were significantly and inversely associated with centenarian females (P < 0.05 for all)." (PMID 34663361, 2021). "Increased urinary albumin excretion in abdominal obesity is considered a consequence of the “organotoxic” influence of hormones produced by adipocytes." (PMID 33456602, 2020). "We also found new biochemical markers of PCOS in women with abdominal obesity, including albumin and total choline." (PMID 28546543, 2017). "First, for the effect of general and central obesity indices on renal function, other blood parameters of renal function such as urinary albumin excretion rates, serum urea and albumin, glomerular filtration rates and micro albuminuria rates must be surveyed." (PMID 24971248, 2012). "In CKD patients and renal transplant patients, urinary albumin excretion rate was also significantly associated with central obesity (data not shown)." (PMID 30305034, 2018). "Recently, some authors also argued that central obesity and related abnormal lipid metabolism were significantly associated with increased urinary excretion of albumin, regardless of glycemic status." (PMID 28715448, 2017). "Ethnic differences in the association between central obesity and raised albumin-creatinine ratio (ACR) have not been investigated." (PMID 22564356, 2012). "Subjects were younger and had less favorable metabolic parameters (i.e., higher abdominal obesity, increased level of TC, TG, LDL-C, fasting glucose, HOMA-IR, and CRP levels), as baseline albumin quartiles increased." (PMID 28430803, 2017). "In conclusion, women with PCOS and abdominal obesity (waist circumference⩾98 cm) had an altered metabolic profile in terms of HDL subclasses, total choline, albumin, apolipoprotein A1 and Apo B/Apo A1 ratio." (PMID 28546543, 2017). "Age, physical inactivity, abdominal obesity, a low LDL level, an elevated fasting glucose level, uric acid and urinary albumin to creatinine ratio (ACR) were correlated with log-CRP." (PMID 26193292, 2015).
central obesity (continued). "Alterations in HDL lipid profile, Apo A1 and albumin levels were most significant in those women within the stratum of highest waist circumference whereas those without central obesity were very similar to the reference population." (PMID 28546543, 2017).
chronic liver failure (35 papers, 2009 to 2025). Liver failure that develops slowly and gradually for some time, possibly for years, often as the result of cirrhosis, or malnutrition. "And transplanted them into Fah-deficient mice with chronic liver failure and found that 3D-printed bodies acquired a wide range of liver functions such as albumin secretion, drug metabolism and glycogen storage after 7 days of differentiation." (PMID 36518541, 2022). "Albumin has seen a recent resurgence due to the positive results seen in the RELIEF study where albumin dialysis was used via the molecular adsorbent recirculating system (MARS) to treat 189 patients with acute on chronic liver failure." (PMID 39212845, 2024). "Indicators of chronic liver failure were observed, with mildly low albumin level 36 g/L (normal 37–56) and a normal serum alpha‐fetoprotein (AFP) level." (PMID 39512434, 2024). "Oxidized albumin (oxHSA) is elevated in several pathological conditions, such as decompensated cirrhosis, acute on chronic liver failure and liver mediated renal failure." (PMID 37926735, 2023). "In the recent ATTIRE (Albumin to Prevent Infection in Chronic Liver Failure) trial, authors aimed to evaluated the effect of albumin infusion, known to modulate circulating PGE2 levels and the associated immune dysfunction." (PMID 35432367, 2022). "Plasma samples were collected on days 1, 5, 10, and 15 from participants recruited into the albumin to prevent infection in chronic liver failure feasibility study." (PMID 31446184, 2020). "Albumin To PrevenT Infection In Chronic LiveR FailurE stage 2 is a multicenter, open-label, interventional RCT and began recruitment in April 2016." (PMID 28911947, 2018). "Recently and again in the liver, it was shown that the immunomodulatory and antioxidant function of albumin stabilizes the endothelium and improves survival in a rodent model of chronic liver failure." (PMID 26161641, 2015). "To investigate this, we used Albumin to Prevent Infection in Chronic Liver Failure (ATTIRE) data to evaluate whether antibiotic use in patients without infection prevented HAI." (PMID 35970815, 2023). "This approach might be particularly attractive given the emerging therapeutic value of plasma exchange and/or the well-documented usefulness of plasma products such as albumin in the treatment of both acute and chronic liver failure." (PMID 33593348, 2021). "The Molecular Adsorbent Recirculating System (MARS), a cell-free albumin dialysis device, has been shown to remove albumin bound compounds and toxins and to exert a number of beneficial hemodynamic effects in patients with acute and acute-on-chronic liver failure." (PMID 21527982, 2011). "We therefore proposed transfusing 20% human albumin solution (HAS) to antagonise the effects of PGE26 and prevent infection in our randomized controlled trial (RCT), ATTIRE (Albumin to Prevent Infection in Chronic Liver Failure)." (PMID 31446184, 2020). "In regard to this, recent data indicate that albumin dialysis using the MARS device is an effective approach for improving hepatic encephalopathy in patients with different clinical conditions, but particularly in patients with acute-on-chronic liver failure." (PMID 19175915, 2009). "No benefits of albumin supplementation were discerned in the “Midodrine and Albumin for Cirrhotic Patients in the Waiting List for Liver Transplantation” (MACHT) or the “Albumin To Prevent Infection in Chronic Liver Failure” (ATTIRE) randomized controlled trials (RCT)." (PMID 34836265, 2021).
left ventricular hypertrophy (35 papers, 2006 to 2025). Enlargement of the LEFT VENTRICLE of the heart. "A similar study showed that albumin-adjusted serum calcium was positively associated with an increased risk of left ventricular hypertrophy in T2DM patients." (PMID 35498438, 2022). "Of the potential novel risk factors for incorporation in to prognostic models albumin (I2 = 66.4%), urate (I2 = 78.3%) and left ventricular hypertrophy (I2 = 72.1%) showed substantial levels of heterogeneity." (PMID 29561894, 2018). "In addition to established traditional general population cardiovascular risk factors, left ventricular hypertrophy, serum albumin, phosphate, urate and hemoglobin were all found to be statistically significant in their association with future cardiovascular events." (PMID 29561894, 2018). "Key predictors of MACEs included antiplatelet use, the grade of left ventricular hypertrophy, and serum albumin levels." (PMID 40361880, 2025). "Albuminuria was defined as a urinary albumin-to-creatinine ratio of ≥ 30 mg/g, and left ventricular hypertrophy according to the Cornell product index." (PMID 31462932, 2019). "TOD were assessed by the following 4 parameters: left ventricular mass index (LVMI or LVH, left ventricular hypertrophy), estimated glomerular filtration rate (eGFR< 60 ml/min/1.73m2), albumin-to-creatinine ratio (ACR ≥ 30 mg/g) and carotid intima-media thickness (cIMT) or plaque." (PMID 33308181, 2020). "Based on the findings of this systematic review, at a minimum, the development of CKD CV prognostic models should assess traditional and non-traditional CV risk factors including left ventricular hypertrophy, serum albumin, hemoglobin, phosphate, and urate." (PMID 29561894, 2018). "Besides, the addition of albumin, hemoglobin, estimated glomerular filtration rate, proteinuria, left atrial diameter >4.7 cm, left ventricular hypertrophy or left ventricular ejection fraction<50% to the FRS model significantly improves the predictive values for cardiovascular events." (PMID 23527293, 2013). "Patients had ≥1 sign of TOD: electrocardiographic left ventricular hypertrophy (LVH), brachial-ankle pulse wave velocity (baPWV) ≥1400 cm/s, or urinary albumin-to-creatinine ratio (ACR) ≥3.5 mg/mmol in women and ≥2.5 mg/mmol in men." (PMID 39091669, 2024). "Age, sex, race, smoking status, systolic blood pressure, heart rate, left ventricular hypertrophy, history of CAD, serum glucose, creatinine, albumin levels, and NT-pro BNP." (PMID 36204571, 2022). "Further, it is important to note that reductions in central blood pressures are superior to reductions in brachial blood pressures with regard to predicting improved subclinical outcomes such as left ventricular hypertrophy, carotid IMT, and urinary albumin secretion." (PMID 35350685, 2022). "The association between the masked effect and SBP variability was analyzed in individuals without HMOD (no electrocardiographic left ventricular hypertrophy, spot urine albumin-to-creatinine ratio < 30 mg/g, and estimated glomerular filtration rate ≥ 60 mL/min/1.73 m2, n = 296)." (PMID 36517899, 2022). "Additionally, non-dipper patients have shown greater left ventricular hypertrophy, greater urinary albumin excretion, deterioration in renal function, and significant elevation of fibrinogen throughout the year when compared to dippers." (PMID 35682067, 2022).
leukopenia (35 papers, 2014 to 2025). "Preoperative albumin level (OR 0.82, 95% CI 0.69–0.99, p = 0.04) was independently associated with the risk of leukopenia." (PMID 36814253, 2023). "Baseline serum protein, albumin, and bilirubin levels were initially associated with leukopenia in our univariate analysis." (PMID 38259414, 2023). "Univariate analysis revealed that baseline serum protein, albumin, and bilirubin levels were significantly associated with the development of leukopenia." (PMID 38259414, 2023). "Notably, patients with lower baseline serum protein, albumin, and bilirubin levels might be predisposed to an increased risk of developing leukopenia." (PMID 38259414, 2023). "Higher level of ALB was correlated with less leukopenia; torasemide and rs2236225 were related to more leukopenia." (PMID 40832604, 2025). "In contrast, leukopenia and normal albumin, bilirubin, and creatine kinase levels were more common in non-ICU patients." (PMID 39998034, 2025). "In a recent prospective multi-center randomized clinical trial, enteral nutrition was proven to alleviate BWL, reduce serum albumin/hemoglobin decline, and decrease grade 3/4 leukopenia rate during dCRT for unresectable EC patients." (PMID 35629373, 2022). "Six patients were excluded from the study due to age < 20 years, four due to pregnancy, nine due to leukopenia or hyperleukocytosis, six due to hemolysis, ten had received albumin or heparin treatment before HBP measurement, and four were measurement outliers." (PMID 35750778, 2022). "Presence of leucocytosis or leukopenia, elevated neutrophil count, elevated C‐reactive protein (CRP), decreased eGFR, increased urea, increased alkaline phosphatase (ALP), decreased albumin, and increased sodium were associated with 28 day mortality." (PMID 35257497, 2022). "Aspartate aminotransferase (AST) and alanine aminotransferase (ALT) were both elevated, and decreased albumin and leukopenia were reported in several studies." (PMID 34003850, 2021). "As our results showed, both case 2 and case 3 showed signs of leukopenia; similarly, case 1, case 2, case 3, and case 6 had an inverted ratio of albumin to globulin." (PMID 33042803, 2020). "The TNuF regimen significantly improves cachectic symptoms, including maintenance of body weight, increase of serum albumin, decrease of inflammatory cytokines and rescue of cachectic leukopenia." (PMID 31426614, 2019). "Univariate analysis identified serum proteins, albumin, and bilirubin as significantly associated with leukopenia, but these factors were not significant according to multivariate analysis." (PMID 38259414, 2023). "Of note, most of these associations remained unaffected by adjustment for age and sex: presence of leucocytosis/leukopenia, increased neutrophil count, elevated CRP, decreased eGFR, elevated urea, decreased albumin, and elevated sodium retained their association with 28 day mortality." (PMID 35257497, 2022). "She had leukopenia (leukocytes 3.410×109/L) and liver function damage [increased aspartate aminotransferase (97 U/L), lactate dehydrogenase (377 U/L), and alanine aminotransferase (92 U/L) levels and decreased albumin (24.8 g/L) and leukocyte ratio (1.18)]." (PMID 36211956, 2022). "Cases were more likely to have leukopenia, low albumin and had lower mean hemoglobin than controls." (PMID 33706821, 2021). "Furthermore, our analysis also indicated that enteral nutrition could significantly reduce the declination in levels of serum albumin and haemoglobin, reduce the rates of grade 3/4 leukopenia and infection, and increase the chemoradiotherapy completion rates." (PMID 35280748, 2022). "The skin necrosis group had a significantly higher incidence of APACHE score, postoperative intubation, Intensive care unit stay, septic shock, leukopenia, higher counts of banded leukocytes, elevated C-reactive protein (CRP), and lower serum albumin level." (PMID 37891231, 2023).
leukopenia (continued). "Factors, such as enlarged liver, spleen and lymph nodes, digestive system involvement, low hemoglobin, leukopenia, CRP, decreased albumin, anti-dsDNA antibody, glucocorticoids, and cyclophosphamide, were independent risk factors for noninfectious fever in SLE." (PMID 30847312, 2019). "The results showed that enlarged liver, spleen and lymph nodes, digestive system involvement, low hemoglobin, leukopenia, CRP, decreased albumin, anti-dsDNA antibody, glucocorticoids, and cyclophosphamide were associated with noninfectious fever in SLE." (PMID 30847312, 2019). "The following factors were closely associated with fever: patient age, treatment history, SLEDAI score, enlarged liver, spleen and lymph nodes, low hemoglobin, leukopenia, CRP, complement C3, albumin, anti-dsDNA antibody, glucocorticoids, and cyclophosphamide." (PMID 30847312, 2019). "In addition, fever upon triage, leukopenia, WBC count, hemoglobin level, albumin level, blood glucose, HbA1c, CRP, and ESR also showed significant differences between IFS and NIFS patients." (PMID 36547572, 2022). "Corroborating our in vitro findings, serial injection of 21- to 24-day-old Control mice with rAFP, but not with the closely related family member albumin, resulted in a leukopenia of comparable severity to that seen in Control mice injected with Sco1hep plasma." (PMID 36301669, 2023).
Parkinson disease (35 papers, 2011 to 2025). A progressive degenerative disorder of the central nervous system characterized by loss of dopamine producing neurons in the substantia nigra and the presence of Lewy bodies in the substantia nigra and locus coeruleus. "The independent risk factors were old age (> 74 years), past cerebral stroke, Parkinson’s disease, low serum albumin levels (< 40.5 g/L), and low hemoglobin levels (< 105 g/L)." (PMID 40370727, 2025). "Univariate analysis showed a significant difference in six factors: age, living alone, past cerebral stroke, Parkinson’s disease, serum albumin, and hemoglobin (P < 0.05)." (PMID 40370727, 2025). "Old age (> 74 years), past cerebral stroke, Parkinson’s disease, low serum albumin level (< 40.5 g/L), and low hemoglobin level (< 105 g/L) were regarded as independent risk factors." (PMID 40370727, 2025). "Univariate analysis was conducted on variables that demonstrated statistical significance, including age (> 74 years), living alone, past cerebral stroke, Parkinson’s disease, serum albumin level (< 40.5 g/L), and hemoglobin level (< 105 g/L)." (PMID 40370727, 2025). "The curcumin-loaded human serum albumin nanoparticles ameliorated Parkinson’s disease features in the C. elegans model, including body movement, basal slowing response, and the degeneration of dopaminergic neurons." (PMID 35269246, 2022). "Studies investigating a surrogate marker of BBB permeability, namely CSF/serum albumin ratio, have shown in Parkinson’s disease, that this ratio increases with disease severity along with amyloid beta (Aβ) and total tau." (PMID 32714664, 2020). "Liver growth factor (LGF) is a hepatic albumin–bilirubin complex with activity as a tissue regenerating factor in several neurodegenerative disorders such as Parkinson’s disease and Friedreich’s ataxia." (PMID 33276671, 2020). "In addition, oxidized ALB has been suggested as an oxidative stress marker in such diseases as Alzheimer and Parkinson's disease." (PMID 35281459, 2022). "PLGA-albumin nanoparticles containing dopamine showing enhanced permeability to the brain through the interaction of albumin with special cell surface receptors in Parkinson's disease model in mice." (PMID 36545269, 2022). "At the 2019 International Congress on Alzheimer's and Parkinson's (AD/PD) Grifols reported significant differences at endpoint between patients in the high albumin/high IVIG treatment arm and the control subjects in tests of memory, language, processing speed, and quality of life." (PMID 32547478, 2020). "Taken together, the administration of dopamine-loaded albumin/PLGA nanosystems suggests a potentially innovative and efficacious drug delivery system for the symptomatic treatment of Parkinson’s disease." (PMID 34312413, 2021). "Albumin was measured in cerebrospinal fluid and serum samples obtained from 73 non-demented subjects with idiopathic Parkinson’s disease and 47 age-matched control subjects." (PMID 22870899, 2012). "However, there is no information available about whether human albumin can prevent loss of tyrosine hydroxylase (TH) expression of dopaminergic (DA) neurons induced by 6-hydroxydopamine (6-OHDA) toxicity that is most commonly used to create a rat model of Parkinson's disease (PD)." (PMID 22815976, 2012).